HAPLN1 (hyaluronan and proteoglycan link protein 1)
Description:
Stabilizes the aggregates of proteoglycan monomers with hyaluronic acid in the extracellular cartilage matrix.
Synonyms: CRTL1; CRT1
Tractability: Antibody: its Gene Ontology location is reachable by antibodies, with high confidence; UniProt places it where antibodies can reach, with medium confidence. PROTAC: its protein half-life has been measured.
Gene: Protein-coding gene on chromosome 5 (83,637,805 to 83,723,528, reverse strand). Ensembl gene ENSG00000145681.
Subcellular location: Secreted, extracellular space, extracellular matrix
Subcellular location (Human Protein Atlas): Vesicles; Predicted to be secreted
Pathways (Reactome):
Extracellular matrix organization: ECM proteoglycans
Gene Ontology:
Molecular function: extracellular matrix structural constituent conferring compression resistance; hyaluronic acid binding
Biological process: central nervous system development; skeletal system development; cell adhesion
Cellular component: extracellular matrix; gel phase of interstitial matrix; extracellular region; perineuronal net; synapse
Genetic constraint (gnomAD): Loss-of-function variants: 11 observed, 28.45 expected, observed/expected ratio (o/e) 0.39, 90% interval 0.24 to 0.64. The upper end of that interval is the gene's LOEUF score, 0.64, which puts it in group 2 of 6, group 1 being the genes least tolerant of losing a copy. Missense variants: 341 observed, 380.83 expected, observed/expected ratio (o/e) 0.9, 90% interval 0.82 to 0.98. Synonymous variants: 169 observed, 148.23 expected, observed/expected ratio (o/e) 1.14, 90% interval 1 to 1.29.
Homologues: Orthologues: chimpanzee HAPLN1 (99% identical), macaque HAPLN1 (98% identical), pig HAPLN1 (97% identical), mouse Hapln1 (96% identical), rabbit HAPLN1 (96% identical), dog HAPLN1 (95% identical), rat Hapln1 (95% identical), guinea pig HAPLN1 (93% identical), tropical clawed frog hapln1 (80% identical), zebrafish hapln1b (74% identical), zebrafish HAPLN1 (72% identical). Paralogues in human: HAPLN3 (52% identical), HAPLN4 (48% identical), HAPLN2 (42% identical), NCAN (39% identical), VCAN (39% identical), BCAN (38% identical), ACAN (38% identical).
Diseases named in the same sentence as HAPLN1 in open-access papers:
HAPLN1 is named in the same sentence as 57 diseases in open-access papers, as found by Europe PMC text mining. Sharing a sentence is not in itself a finding about the gene and the disease. The quoted sentences say what the papers report.
melanoma (27 papers, 2011 to 2025). A malignant, usually aggressive tumor composed of atypical, neoplastic melanocytes. "HAPLN1 is also associated with peritoneal metastasis in the pancreatic cancer, but its expression can inhibit lymph node metastasis in melanoma, suggesting context-specific functionality." (PMID 38791985, 2024). "The restoration of HAPLN1 can improve mononuclear immune cell mobility and cause melanomas to metastasize to lymph nodes more than to visceral organs." (PMID 37174106, 2023). "The increase of lymphatic endothelial permeability, due to HAPLN1 loss, promotes migration and invasion of melanoma cells, and their escape from the lymphatic system to distant metastatic sites." (PMID 34067929, 2021). "Age-related loss of the hyaluronan and proteoglycan link protein 1 (HAPLN1), which directly binds hyaluronan, has also been associated with increased lymph node permeability and increased lymphatic metastasis in melanoma." (PMID 33014869, 2020). "HAPLN1 can increase the permeability of lymphatic vessels by downregulating VE-cadherin in lymphatic ECs, which may contribute to in-transit metastases in melanoma, but this is associated with an increased risk of visceral metastases." (PMID 38791985, 2024). "Age-related changes in dermal collagen architecture induced by HAPLN1 has been linked to reduced T cell motility and infiltration, and increased melanoma incidence with age, raising the possibility that ECM remodeling represented by our matrix risk signature captures a similar process in SqCC." (PMID 36404344, 2022). "Age-related loss of HAPLN1 was shown to be associated with loss of integrity in the lymphatic vasculature and with enhanced lymphatic endothelial permeability, which enabled the escape of melanoma cells from the lymphatic system to distant metastatic sites." (PMID 31428105, 2019). "Proteomic analyses of CM-EVs demonstrated an enrichment of proteins including p120-catenin, radixin, annexins A1/A2, syntenin, hyaluronan and proteoglycan link protein 1 (HAPLN1) involved in angiogenesis, cell invasion, migration and metastasis in melanoma." (PMID 38589876, 2024). "A loss of HAPLN1 in aging fibroblasts leads to structural changes in ECM and promotes melanoma cell migration." (PMID 38791985, 2024). "HAPLN1′s deletion of ECM not only increases the invasion ability of melanoma cells but also prevents the occurrence of T-cell infiltration into tumor sites." (PMID 37174106, 2023). "In their studies, they showed that a decrease in HAPLN1 and the remodeling of collagen in the skin during aging stimulates melanoma metastasis." (PMID 34638400, 2021). "The decrease in HAPLN1 protein results in the disruption of the vascular basement membrane and induces vessel permeability, and this enhances melanoma metastasis." (PMID 34966673, 2021). "Treatment of melanomas with recombinant HAPLN1 inhibits tumour growth as a result of increased cytotoxic T-cell infiltration, leading to the conclusion that loss of HAPLN1 inhibits T-cell based rejection of melanoma through effects on ECM structure." (PMID 33187209, 2020). "Supporting our data, a bioinformatics study predicted HAPLN1 expression to lie downstream upregulated Wnt/β-catenin signaling in colorectal cancer and proteomics analysis of tumor stroma reported HAPLN1 in highly metastatic melanomas." (PMID 27191501, 2016). "The protein with the greatest differential expression in melanoma exosomes is hyaluronan and proteoglycan link protein 1 (HAPLN1)." (PMID 23056502, 2012). "HAPLN1 is also involved in melanoma development and extracellular matrix remodeling during the process of melanoma cell migration and melanoma progression." (PMID 23056502, 2012). "We also used proteomic analysis and discovered differentially expressed melanoma exosomal proteins, including HAPLN1, GRP78, syntenin-1, annexin A1, and annexin A2." (PMID 23056502, 2012). "The NC clusters Hapln1 and Aqp1 expressed melanoma dissemination and NC cell migration genes." (PMID 37605008, 2023).
melanoma (continued). "The preservation of normal ECM function of HAPLN1 may be of importance as down-regulation of HAPLN1 could destabilize the ECM making it more permeable to cancer invasion of melanoma and colorectal cancer." (PMID 36625202, 2023). "Furthermore, in melanoma, aged fibroblasts express low levels of hyaluronan and proteoglycan link protein 1 (HAPLN1), which is an ECM-modifying protein involved in the cross-linking of hyaluronan to the ECM." (PMID 34067929, 2021). "Interestingly, age-related changes in HAPLN1 were also shown to increase lymphatic permeability, which affected melanoma lymph node metastasis." (PMID 31428105, 2019). "Further research investigating the role of HAPLN1 in exosomes may uncover novel mechanisms to explain potential roles for exosomes in melanoma progression." (PMID 23056502, 2012). "Additionally, HAPLN1 may also prove to be important clinically, as it is a specific exosomal protein that could be the focus of future melanoma biomarker studies." (PMID 23056502, 2012). "Compared with younger patients with melanoma, older patients exhibit more pronounced ECM alterations owing to changes in hyaluronan and proteoglycan link protein 1 (HAPLN1), which can enhance the invasiveness and metastatic potential of melanoma cells." (PMID 39897036, 2025). "Annexin A1, annexin A2, syntenin-1 and hyaluronan and proteoglycan link protein 1 (HAPLN1) were among these proteins, all involved in processes related to melanoma progression, such as angiogenesis, cell invasion, migration and metastasis." (PMID 36704194, 2022). "Aged human skin fibroblast expresses reduced levels of hyaluronan and proteoglycan link protein 1 (HAPLN1) leading to a more organized ECM, which promotes the metastasis of melanoma cells." (PMID 35966762, 2022). "For instance, the decrease of hyaluronan and proteoglycan link protein 1 (HAPLN1) in aged fibroblasts was shown to lead to less contractile ECM that impeded the infiltration CD4+ and CD8+ T cells, and promoted metastasis of melanoma cells." (PMID 34852849, 2021). "In melanoma, aged fibroblasts express lower amounts of the ECM-modifying protein hyaluronan and proteoglycan link protein 1 (HAPLN1) that leads to reduced integrity of lymphatic vasculature and increased metastasis." (PMID 33037194, 2020). "HAPLN1 is an extracellular matrix mucopolysaccharide that has been previously shown to promote metastasis in cancer cells, including B16F10 melanoma." (PMID 23056502, 2012). "Also, in melanoma, there is evidence that aging fibroblasts were less capable of secreting ECM, especially HAPLN1, resulting in a more aligned ECM that promoted metastasis of melanoma cells." (PMID 34646782, 2021).
gastric cancer (12 papers, 2022 to 2025). A primary or metastatic malignant neoplasm involving the stomach. "The Kaplan–Meier analysis indicated that higher HAPLN1 level was associated with a shorter overall survival (OS) in gastric cancer patients (P = 0.003)." (PMID 34724589, 2022). "To dissect the mechanism underlying HAPLN1 up-regulation in CAFs, we first treated human stomach fibroblast cell line Hs738 with the condition medium (CM) of human gastric cancer cell lines, AGS cells and MKN45 cells." (PMID 34724589, 2022). "HAPLN1 was identified as the most significantly up-regulated gene in CAFs of gastric cancer, and higher HAPLN1 levels were associated with shorter overall survival." (PMID 34724589, 2022). "Our bioinformatics analysis of DEGs between CAFs and NFs, as well as the validation studies have implicated that HAPLN1 is mainly derived from CAFs in gastric cancer." (PMID 34724589, 2022). "CAFs-derived HAPLN1 is associated with disease progression and poor prognosis in gastric cancer, and CAFs-derived HAPLN1 enhances gastric cancer cell invasiveness through extracellular matrix remodeling." (PMID 34724589, 2022). "Collectively, HAPLN1 expression in gastric cancer is associated with the disease progression and poor outcome." (PMID 34724589, 2022). "Similarly, gastric cancer patients with high HAPLN1 levels in their cancer-associated fibroblasts showed shorter OS." (PMID 36625202, 2023). "For example, miR-374a-5p-loaded EVs of gastric cancer-derived MSCs target HAPLN1 to increase the expression of integrins in gastric tumors and promote gastric cancer cell migration." (PMID 40078996, 2025). "Another study suggested that gastric CAFs remodel the ECM via the production of hyaluronan and proteoglycan link protein 1 (HAPLN1) and promote the invasion of gastric cancer cells." (PMID 38562556, 2024). "Despite recent findings that CAF-derived HAPLN1 promotes tumor invasion in gastric cancer, our data reveal that HAPLN1 is predominantly expressed in NAT tissues, with expression levels sharply decreasing in tumor tissues." (PMID 39305996, 2024). "CAFs-derived hyaluronan and proteoglycan link protein 1 (HAPLN1) can remodel the extracellular matrix, and facilitates tumour invasion in gastric cancer." (PMID 38862740, 2024). "Elevated HAPLN1 expression in CAFs enhances gastric cancer invasion and metastasis via ECM remodeling." (PMID 39850884, 2024). "The authors also showed that gastric cancer cells stimulate the HAPLN1 synthesis by CAFs by activating the TGF-β/SMAD signaling pathway." (PMID 38562556, 2024). "Hyaluronan and proteoglycan link protein 1 (HAPLN1) is shown to be upregulated in CAFs in gastric cancer." (PMID 37686288, 2023). "Given that HAPLN1 is the main ECM-modifying protein, we further identified that HAPLN1 is mainly produced by CAFs in human gastric cancer microenvironment, which is associated with the disease progression and poor prognosis." (PMID 34724589, 2022). "In the present study, we performed bioinformatics analysis, and identified hyaluronan and proteoglycan link protein 1 (HAPLN1) as the most significantly up-regulated gene in CAFs compared with the respective normal fibroblasts (NFs) of human gastric cancer." (PMID 34724589, 2022). "We herein demonstrated that HAPLN1 expression in gastric cancer tissues was increased with relative to the normal stomach tissues." (PMID 34724589, 2022). "In the present study, we identify HAPLN1 as the most significantly up-regulated molecule in CAFs compared with the corresponding NFs of gastric cancer." (PMID 34724589, 2022). "HAPLN1 mRNA levels in tumour tissues were positively associated with the T staging, LNM and TNM stage in gastric cancer." (PMID 34724589, 2022). "Both the mouse xenograft model study and human gastric cancer tissue assays indicated that HAPLN1 can reduce the number, density, width and length of collagen fibers in ECM, and increase the fiber alignment." (PMID 34724589, 2022).
gastric cancer (continued). "We further investigated the causative association between HAPLN1 expression with tumour differentiation and ECM in human gastric cancer." (PMID 34724589, 2022). "Our studies shed a light on the role of CAFs-derived HAPLN1 in the pathogenesis of gastric cancer, and should provide novel CAFs-based strategies for the prevention and treatment of gastric carcinoma." (PMID 34724589, 2022). "In gastric cancer, hyaluronan and proteoglycan link protein 1 (HAPLN1) were the most significantly upregulated genes in fibroblasts." (PMID 36341377, 2022). "We focused on the function of HAPLN1, and found that HAPLN1 promoted gastric cancer cell migration and invasion in vitro and in vivo." (PMID 34724589, 2022). "We identified herein that gastric cancer cell-derived TGF-β1 up-regulates HAPLN1 expression in stomach fibroblasts through TGF-β1/Smad signaling activation." (PMID 34724589, 2022). "Gastric cancer cells can activate fibroblasts to up-regulate HAPLN1 expression via activation of TGF-β1/Smad2/3 signaling." (PMID 34724589, 2022). "We then performed the validation studies to further confirm that the serum HAPLN1 levels in gastric cancer patients were much higher than those in healthy controls (836.4 ± 60.88 ng/ml vs 606.8 ± 73.37 ng/ml, P < 0.001)." (PMID 34724589, 2022). "Mechanically, gastric cancer cells activate fibroblasts to up-regulate HAPLN1 expression via activation of TGF-β1/Smad2/3 signaling, which in turn promotes tumour migration and invasion." (PMID 34724589, 2022). "Collectively, our study demonstrated that gastric cancer cells promote HAPLN1 production in CAFs via activation of TGF-β1/Smad signaling." (PMID 34724589, 2022). "This study sheds light on the role of CAFs-derived HAPLN1 in the pathogenesis of gastric cancer, and provides insights for the development of novel strategies for prevention and treatment of gastric carcinoma." (PMID 34724589, 2022). "We next investigated the effects of HAPLN1 on biological functions of gastric cancer cells." (PMID 34724589, 2022). "The IHC assays further showed that high HAPLN1 levels were observed in 51.61% patients with locally advanced gastric cancer, and its levels were positively correlated with tumour T staging (P < 0.0001), lymph node metastasis (LNM) (P = 0.0006) and TNM stage (P = 0.0063)." (PMID 34724589, 2022). "HAPLN1 could be detected in gastric cancer patients’ sera, and its serum levels in patients were higher than those in the healthy controls." (PMID 34724589, 2022). "Importantly, neutralization of TGF-β1 activity with an anti-TGF-β1 monoclonal antibody (Biolegend, San Diego, USA) could prevent the increase of HAPLN1 expression and production in Hs738 cells induced by gastric cancer cell CM." (PMID 34724589, 2022). "For instance, in gastric cancer, CAFs stimulated by TGF-β1/Smad2/3 signaling significantly upregulate hyaluronan and proteoglycan link protein 1 (HAPLN1), enhancing tumor migration and invasion." (PMID 40313969, 2025). "In gastric cancer, TGF-β activates downstream Smad2/3 to upregulate the hyaluronan and proteoglycan link protein 1 (HAPLN1) production, which drives ECM remodeling." (PMID 40248695, 2025). "For example, in gastric cancer, CAFs activated by TGF-β1/Smad2/3 signaling can highly express hyaluronan and proteoglycan link protein 1 (HAPLN1), promoting tumor migration and invasion." (PMID 38602594, 2024). "Gastric cancer cells activate fibroblasts via the TGF-β1/Smad2/3 signaling pathway, enhancing HAPLN1 expression to promote tumor migration and invasion." (PMID 39850884, 2024). "The clinical relevance of hyaluronan and proteoglycan link protein 1 (HAPLN1) was investigated using TCGA data and human gastric cancer specimens." (PMID 34724589, 2022). "We further reveal that gastric cancer cells can activate fibroblasts to up-regulate HAPLN1 expression via the TGF-β1/Smad2/3 signaling activation, and that CAFs-derived HAPLN1 promotes tumour invasion through ECM remodeling." (PMID 34724589, 2022).
gastric cancer (continued). "Studies using the human gastric cancer cell lines and the primary gastric cancer CAFs or NFs revealed that HAPLN1 was mainly expressed in the fibroblasts rather than in cancer cells of HGC27, MKN45, AGS, MGC803 and SGC7901 cells." (PMID 34724589, 2022).
multiple myeloma (6 papers, 2021 to 2024). "In addition, HAPLN1 was shown to have the properties of an oncogene contributing to an increased susceptibility to lung cancer, aggressiveness of hepatocellular carcinomas, and drug resistance to multiple myeloma." (PMID 35720292, 2022). "This study defines ectopic mitochondrial chaperonin 60 (CH60) on the multiple myeloma cell surface as a HAPLN1 matrikine receptor that signals via TLR4 to induce NF-κB signaling and drug resistance." (PMID 36625202, 2023). "In multiple myeloma cells, HAPLN1 can activate the NF-ƙB pathway to acquire resistance to bortezomib." (PMID 35720292, 2022). "For example, Multiple Myeloma cells incubated in medium containing two extracellular matrix proteins: hyaluronan and proteoglycan link protein 1 (HAPLN1) displayed increased levels of cell proliferation despite BTZ treatment when compared to the same cells incubated only with BTZ." (PMID 33972578, 2021).
malignant pleural mesothelioma (5 papers, 2011 to 2024). A malignant neoplasm that arises from mesothelial cells in the pleura and shows a diffuse growth pattern. "Hyaluronan-linked protein 1 (HAPLN1) which has been shown to be highly expressed in malignant pleural mesotheliomas (MPM), was detected in serum using an electrochemical surface-imprinting method." (PMID 23516416, 2013). "An upregulation of HAPLN1 has been reported in pancreatic cancer and malignant pleural mesothelioma, while its expression is lost in CRC." (PMID 38791985, 2024). "HAPLN1 expression is upregulated in pancreatic cancer and malignant pleural mesothelioma, but its expression is lost in colorectal cancer (CRC)." (PMID 38791985, 2024). "The pro-tumorigenic role of VCAN/HAPLN1 complex has been tested in several other tumor types, such as malignant pleural mesothelioma and breast and prostate cancers and increased tumor-specific VCAN expression levels have been reported in ACC and several other tumor types." (PMID 25587024, 2014). "Hyaluronan- and proteoglycan link protein 1 (HAPLN1), which was also downregulated, has been shown to play a pro-tumorigenic role in malignant pleural mesothelioma." (PMID 21731601, 2011).